YES1 (YES proto-oncogene 1, Src family tyrosine kinase)
Diseases named in the same sentence as YES1 in open-access papers (continued):
Sharing a sentence is not in itself a finding about the gene and the disease.
cancer (41 papers, 2014 to 2026). A tumor composed of atypical neoplastic, often pleomorphic cells that invade other tissues. "High expression of YES1 in cancer has been closely associated with a poor prognosis." (PMID 36909198, 2023). "Although the effect of YES1 on the YAP1/TAZ pathway has been reported in cancer studies, the understanding of its role in the cardiovascular processes remains unexplored." (PMID 40131761, 2025). "It is expected that YES1 can be activated in the process of cancer drug resistance, and the activation serves as a compensatory mechanism for the signal transduction inhibited by target therapy." (PMID 38338729, 2024). "Several reports have previously demonstrated the involvement of YES1 expression in cancer metastasis." (PMID 38338729, 2024). "In this section, we will focus on the function and control of YES1 in both the development of cancer and the mechanisms of resistance to cancer drugs." (PMID 38338729, 2024). "The circFUT8/miR-944/YES1 axis can inhibit the apoptosis of NSCLC cancer cells and promote tumor growth in the H522 cell xenograft nude mice model." (PMID 36077769, 2022). "In NSCLC, matrine inhibits CircFUT8/miR-944/YES1 axis, which in turn hinders cancer cell migration, invasion, and cell cycle, and promotes apoptosis." (PMID 36077769, 2022). "When YAP1 is phosphorylated by YES1, this complex enters the nucleus and localizes to the promoters of anti-apoptotic genes, driving cancer transformation and survival." (PMID 36532767, 2022). "Multiple studies have demonstrated that YES1 functions as an oncogene and is dysregulated in various carcinomas." (PMID 35012539, 2022). "Current reports on YES1 nearly all focus on its role in promoting cell proliferation and inhibiting apoptosis in cancer." (PMID 30341976, 2018). "SFK kinases have been shown to participate to cancer cell proliferation and survival, YES1 being currently considered as a potential therapeutic target in a number of cancers." (PMID 28303961, 2017). "Indeed, we found that WNK1 and YES1 is the common shared kinase by these two cancer cell lines that mediates drug resistance in them amongst other." (PMID 37359373, 2023). "Recent findings suggest that YES1 can be a therapeutic target in cancer." (PMID 37994325, 2023). "YES proto-oncogene 1, Src family tyrosine kinase (YES1), FERM domain containing kindlin 2 (FERMT2), and family with sequence similarity 98 member B (FAM98B) have previous associations with cancers, but our finding that they are associated with BCNHL as high-potential biomarkers is novel." (PMID 36873459, 2022). "This work proposes the therapeutic management of cancer by using natural compounds targeting YES1." (PMID 35630545, 2022). "The Y357 phosphorylation of YAP by YES1 induces the expression of the transcriptional genes BCL2L1 and BIRC5 downstream of YAP, and the small-molecule YES1 inhibitor has been found to suppress the proliferation of β-catenin-dependent cancers in cell lines and in vivo experiments." (PMID 32466572, 2020). "MiR-93 could be considered as a potential prognostic biomarker for PDAC, and miR-93 itself or its protein targets (CRMP2, MAPRE1, or YES1) have been elucidated as potential new therapeutic targets for this cancer." (PMID 32366853, 2020). "YES1 also provides chemotherapeutic resistance in several cancers." (PMID 28818100, 2017). "Importantly, the use of dasatinib, a small molecule inhibitor of YES1, inhibits the proliferation of cancer cell lines dependent on β-catenin activity." (PMID 27589805, 2016). "Therefore, suppressing YES1 activity could be effective in cancers driven by aberrant YAP and β-catenin activity." (PMID 27589805, 2016). "The expression perturbation results of hub PPMEs between normal and cancer samples revealed that hub PPMEs were significantly different between normal and cancer samples, except EGFR, LCK, and YES1, and they had higher expression levels in cancer samples." (PMID 39940833, 2025).
cancer (continued). "miR-944 can participate in three signaling axes to promote cancer cell apoptosis, including the PRNCR1/miR-944/HOXB5, CircCSPP1/miR-944/FZD7, and CircFUT8/miR-944/YES1 signaling axes." (PMID 36077769, 2022). "YES1 is a member of the SRC family kinases (SFKs) which regulate the proliferation, survival, angiogenesis, invasion and migration of cancer cells." (PMID 32744377, 2020). "Inhibition of YES1 – that was found to be down-regulated after LINC00152 silencing both at mRNA and protein levels – was reported to lead to reduced cell proliferation of beta-catenin-dependent cancers." (PMID 32307642, 2020). "By phosphorylation of YAP, YES1 regulates the formation, localization and activity of the YAP-β-Catenin-TBX5 complex, thereby promoting the survival and transformation of β-catenin-active cancer cell lines." (PMID 33158300, 2020). "Indeed, silencing of CCAT1 led to downregulation of many genes involved in cancer cell proliferation, survival and metastasis, such as EGFR, CDK4, YES1, PAK4, and HMGA1." (PMID 30190462, 2018). "YES proto-oncogene 1 (YES1), a non-receptor tyrosine kinase, is found to be crucial for the formation of a transcriptional complex that is required for β-catenin-driven cancers." (PMID 27589805, 2016). "Furthermore, in the Rohrbeck Lung (all-Lung, cancer only) dataset Bcl6 expression was positively correlated with MAP2K4, Yes1 and negatively correlated with Dlg2 and Lgl1." (PMID 26187947, 2015). "Based on the total score, the top 20 tree shrew drug targets included several homologs of targets for cancer chemotherapy, including vascular endothelial growth factor receptor 2 (VEGFR2), membrane metallo-endopeptidase (MME), and the proto-oncogene tyrosine-protein kinase Yes (YES1)." (PMID 25105297, 2014). "In addition, overexpression of miR-140-5p could inhibit proliferation, migration, and invasion and promote apoptosis in cancer by downregulating MAPK1, TRIM28, and YES1, further regulating levels of cleaved caspase-3, Bcl-2, and Bax, and blocking nuclear transport and Wnt/β-catenin signaling." (PMID 34479600, 2021). "AURKA and IDH3B are not present in any of the lists of cancer genes, whereas CDK8, MARCH7, YAP1, and YES1 are found among the more than 9000 candidate cancer genes identified by forward genetic screens in mice." (PMID 33427197, 2021).
tumor (37 papers, 2015 to 2025). "Since silencing of YES1 was lethal to NF2-deficient PRCC tumor cells, their survival was assessed following dasatinib and saracatinib treatment." (PMID 29535838, 2018). "The last gene, YES1, also encodes a small GTPase that has been widely regarded as a tumor associated gene." (PMID 28255556, 2017). "Therefore, YES1 protein expression is positively associated with the tumor-infiltrating Treg population." (PMID 40216744, 2025). "High YES1 protein expression was associated with an increased level of tumor-infiltrating Tregs." (PMID 40216744, 2025). "Persistent YES1 activation promotes tumor growth despite HER2 inhibition, and targeting YES1 with Src inhibitors such as dasatinib has restored T-DM1 sensitivity in preclinical models, suggesting a potential therapeutic avenue." (PMID 40722763, 2025). "In the TCGA LIHC and GTEx datasets, SRC and YES1 were also significantly upregulated in tumor tissues relative to normal liver tissues (p < 0.01 for both), while FGR and FYN remained unchanged." (PMID 40650282, 2025). "Nonetheless, the functions of SFKs, especially SRC and YES1, in altering the tumor microenvironment influenced by fibrosis remain largely unclear." (PMID 39776795, 2025). "YES1 plays a pivotal role in promoting cell proliferation, survival, and invasiveness during tumor development." (PMID 38338729, 2024). "The disruption of YES1 signaling in SCLC models leads to a significant reduction in tumor growth and metastasis, indicating a potential reliance on this oncogenic pathway." (PMID 38338729, 2024). "Recently, reports have focused on alterations in YES1 expression/activity concerning tumor growth, metastasis advancement, and resistance to targeted therapy, considering it a promising new target." (PMID 38338729, 2024). "Alterations in YES1 activity are common in solid tumors, highlighting its role in oncogenic transformation, tumor growth, metastatic progression, and resistance to targeted therapies." (PMID 38338729, 2024). "Imaging of the whole body of mice showed that circ-YES1 knockdown inhibited tumor development and metastasis by decreased the numbers of metastatic foci in lung tissues according to the HE staining." (PMID 37009887, 2023). "The imaging experiment results revealed that circ-YES1 knockdown impeded tumor development and metastasis in a nude mouse xenograft model." (PMID 37009887, 2023). "The YES1 inhibitor CH6953755 has shown anti-tumor activity in YES1-positive organoid models as well as in cell line- and patient-derived xenografts (PDX)." (PMID 38203275, 2023). "Taken together, our results show that circ-YES1 promotes tumor development through the miR-142-3p–HMGB1 axis and support the development of circ-YES1 probability as a new therapeutic NSCLC target." (PMID 37009887, 2023). "We found that OE of YES1 significantly increased GC xenograft tumor development, while KD of YES1 significantly decreased GC xenograft tumor development." (PMID 33941853, 2021). "In present study, we demonstrate that YES1 is highly expressed in human GC tissues and is positively correlated with tumor invasion, regional metastasis, relapse and the poor overall survival rate of GC patients." (PMID 33941853, 2021). "To validate the oncogenic role of YES1 in HCC, we compared the mRNA levels of YES1 between tumor and normal tissues and analyzed the co-expression between YES1 and RBM15." (PMID 34707107, 2021). "In this study, the prognostic relevance of miR-140-5p in GC was investigated and YES1 was identified as a novel target of miR-140-5p in regulating tumor progression." (PMID 28818100, 2017). "Previous studies in different neoplasms have shown that in vitro knock down of YES1 expression induce cell growth and metastasis reduction." (PMID 26444668, 2015). "Since in Drosophila and human cells, Src upregulates Stat activity, tumours showing high Bcl6 and Src or Yes1 expression would be predicted to be sensitive to this combined therapeutic regime." (PMID 26187947, 2015).
tumor (continued). "However, the roles of SFKs, particularly SRC and YES1, in fibrosis-driven tumor microenvironment modification are still not well understood." (PMID 39776795, 2025). "YES1, the most significantly upregulated gene among IO-exposed tumor cells in this cohort, may explain one specific mechanism via YAP1 (YES-associated protein), which is also associated with poor survival in treatment of treatment naïve ccRCC patients." (PMID 39639369, 2024). "YES1 is significantly upregulated in immunotherapy exposed tumor cells." (PMID 39639369, 2024). "Linc01133-overexpression greatly enhanced the xenograft tumor growth compared to the control group (tumor weight: p = 0.0397; tumor volume: p = 0.005), while the growth of YES1-knocked-down xenograft tumors was obviously impeded (tumor weight: p = 0.0317; tumor volume: p = 0.004)." (PMID 35017464, 2022). "YES1 functions as a tumour oncogene and may be a potential therapeutic target in different types of cancers." (PMID 35012539, 2022). "Furthermore, dasatinib treatment was found to significantly inhibit tumor growth in a patient-derived xenograft (PDX) model with high YES1 expression." (PMID 32466572, 2020). "This study aimed to evaluate the prognostic relevance of miR-140-5p in GC and identify whether YES1 is a direct target of miR-140-5p in the regulation of tumor progression." (PMID 28818100, 2017). "The YES1 levels in the tumor tissues were than examined through immunohistochemistry staining." (PMID 28818100, 2017). "Yes1 is considered as a key regulator of CUL9 phosphorylation at Y1505, while mutation of Yes1 or helicobacter-induced CUL9-Y1505 might switch CUL9 from a tumor-suppressor to an oncogene." (PMID 41200507, 2025). "Moreover, YES1 ablation greatly hindered linc01133-induced tumor growth." (PMID 35017464, 2022). "In our differential expression analysis at the cell phenotype level, tumor cells from IO-exposed tumor FOV showed only 15 genes significantly higher than tumor cells from FOV naïve to IO, and YES1 was the most significant (FDR = 0.026)." (PMID 39639369, 2024). "Lastly, in CR-TNBC patient P942, the baseline PDX tumor (BTY14) had high phosphorylation on the shared pTyr sites of SRC, FYN, LCK, YES1, and FGR as well as SFK substrates such as tensin, SHIP-1 (INPP5D), AFAP1L2, paxillin, and PTK2." (PMID 36077757, 2022). "Overexpression of Yes1 also increased LC3B expression and led to cisplatin resistance in a xenograft tumour model." (PMID 35012539, 2022). "YES1-OE and control MGC-803 cells were injected into the spleen of nude mouse, 30 days later, mice were sacrificed, and tumor metastatic nodules in the liver were counted." (PMID 33941853, 2021). "The expressions of YES1 and ANXA2 were significantly related to tumor invasion, regional metastasis and GC relapse during 3-year follow-up period." (PMID 33941853, 2021). "Overexpression (OE) of YES1 increases, while knockdown (KD) of YES1 or ANXA2 decreases GC cell invasion and migration in vitro and tumor growth in mouse models." (PMID 33941853, 2021). "Third, the knockdown of the YES1 gene decreased NSCLC cell proliferation, invasion ability, and tumor growth in vivo." (PMID 32466572, 2020). "Among these DEGs several genes with oncogenic and/or metastasis promoting function (e.g. STC1, YES1, PORCN) were found to be down-regulated and certain tumour suppressor genes (e.g. DKK1, PERP) showed overexpression in LINC00152-silenced cells." (PMID 32307642, 2020). "We found that SRC and YES1 were significantly upregulated in tumor tissues compared to adjacent non-tumoral liver tissues (p < 0.001), confirming their relevance as therapeutic targets in this study." (PMID 40650282, 2025).
tumor (continued). "Moreover, in the mouse tumor xenografts, linc01133 induced increased YAP1 expression both in the cytoplasm and in the nucleus, which were greatly ablated by simultaneous YES1 knockdown." (PMID 35017464, 2022). "In these PDX models, dasatinib treatment did not affect tumor growth in patients with low YES1 expression." (PMID 32466572, 2020). "Amplification of relevant genes, including AKT1, Kirsten rat sarcoma (KRAS), and proto-oncogene tyrosine-protein kinase Yes (YES1), were detected (data not shown) but were not enriched in the osimertinib-resistant xenograft tumor, osimertinib-3." (PMID 29764505, 2018).
infection (2 papers, 2013 to 2024). The state of being infected such as from the introduction of a foreign agent such as serum, vaccine, antigenic substance or organism. "Taken together, our data demonstrate that Y1KI restricts HEV infection in primary cells ex vivo and in rats in vivo, proving the principal role of Yes1 as a critical host factor needed for efficient HEV onset of infection." (PMID 39560373, 2024). "To further reveal which HEV life cycle step is affected by perturbation of Yes1 activation, we performed time-of-addition infection assays." (PMID 39560373, 2024). "In summary, our data indicate that the activity and signaling of Yes1 are needed for the efficient early onset of infection, excluding the initial binding of HEV particles." (PMID 39560373, 2024). "We, therefore, propose Yes1’s signaling to be a critical factor for HEV pathogenesis by creating an optimal environment for the viral onset of infection." (PMID 39560373, 2024). "Future studies have to investigate the interplay of Yes1 and involved receptors to detangle the process of HEV early onset of infections and whether Yes1 could possibly be directly interacting with viral proteins since currently further experiments are limited due to the few available assays." (PMID 39560373, 2024). "Strikingly, by using time-of-addition assays, we found Yes1’s signaling to restrict HEV’s early onset of infection without affecting HEV binding." (PMID 39560373, 2024).
YES1 also shares sentences with these, for which no sentence is quoted: Hypertension (3 papers); pancreatic cancer (2); schizophrenia (2); bipolar disorder (1); brain glioma (1); breast tumors (1); cervical cancer (1); chronic obstructive pulmonary disease (1); clear cell ovarian carcinoma (1); endothelial dysfunction (1); esophageal adenocarcinoma (1); esophageal cancer (1); esophageal squamous cell carcinoma (1); heart failure (1); hypopharyngeal carcinoma (1); leukemia (1); lung squamous cell carcinoma (1); multiple sclerosis (1); myocardial ischemia (1); oral cancer (1); papillary renal cell carcinoma (1); Parkinson disease (1); pulmonary fibrosis (1); renal cell carcinoma (1); Sensory neuropathy (1); urothelial carcinoma (1); –Aldrich syndrome (1).